EIF3C (eukaryotic translation initiation factor 3 subunit C)
Diseases named in the same sentence as EIF3C in open-access papers (continued):
Sharing a sentence is not in itself a finding about the gene and the disease.
cancer (22 papers, 2014 to 2025). A tumor composed of atypical neoplastic, often pleomorphic cells that invade other tissues. "The top three disease and function differentially expressed gene clusters associated with eIF3c silencing were Organismal Injury and Abnormalities, Cancer and Cell Death and Survival." (PMID 31316002, 2019). "EIF3C is abnormally expressed and exerts an important regulatory role in various human cancer physiological processes, such as cell proliferation and tumorigenesis." (PMID 36157221, 2022). "In this study, we focused on eIF3c, because overexpression of eIF3c enhances the translation function and malignancy in cancer cells." (PMID 30680067, 2018). "eIF3C was found to be an oncogene and was shown to be increased in cancer cells, which is confirmed by our findings in CRC." (PMID 29254159, 2017). "Upregulation of eIF3a, eIF3b, eIF3c, eIF3d, eIF3e, eIF3h, and eIF3i along with reduced levels of eIF3e and eIF3f has been observed in several cancers." (PMID 28083147, 2016). "A similar promise has been recently made also for the eIF3c subunit, since the genetic manipulations with its expression in five different cancer cell lines led to cell death." (PMID 24912683, 2014). "eIF3C, a constituent of the largest eukaryotic translation initiation factor eIF3 complex, plays a crucial role in regulating transcript-specific translation during development and exhibits elevated expression levels in various cancer types." (PMID 38274829, 2023). "Previous studies revealed that EIF3C promoted cancer progression via regulating MAPK pathway." (PMID 35650605, 2022). "Thus, the overexpression of eIF3a, eIF3b, or eIF3c subunits stimulates the expression of other eIF3 subunits that further supports the translational components necessary for faster cancer cell growth." (PMID 28083147, 2016). "However, it remains to be addressed whether eIF3c is involved in the resistance to anti-cancer drugs." (PMID 30680067, 2018). "Indeed, several translation initiation factors that are overexpressed in human cancer, including EIF4E, EIF4G, EIF3A, EIF3C, and EIF3H may also contribute to tumorigenesis." (PMID 28594900, 2017).
EIF3C also shares sentences with these, for which no sentence is quoted: lung adenocarcinoma (6 papers); breast carcinoma (4); renal cell carcinoma (2); Acute hepatitis (1); asthma (1); gastric cancer (1); head and neck squamous cell carcinoma (1); infection (1); liver diseases (1); nasopharyngeal carcinoma (1); non-small cell lung carcinoma (1); ovarian adenocarcinoma (1); prostate tumors (1); testicular cancer (1); testicular seminoma (1); ZIKV infection (1).